RRAGD (Ras related GTP binding D)
Description:
Guanine nucleotide-binding protein that plays a crucial role in the cellular response to amino acid availability through regulation of the mTORC1 signaling cascade. Forms heterodimeric Rag complexes with RagA/RRAGA or RagB/RRAGB and cycles between an inactive GTP-bound and an active GDP-bound form: RagD/RRAGD is in its active form when GDP-bound RagD/RRAGD forms a complex with GTP-bound RagA/RRAGA (or RagB/RRAGB) and in an inactive form when GTP-bound RagD/RRAGD heterodimerizes with GDP-bound RagA/RRAGA (or RagB/RRAGB). In its active form, promotes the recruitment of mTORC1 to the lysosomes and its subsequent activation by the GTPase RHEB. This is a crucial step in the activation of the MTOR signaling cascade by amino acids. Also plays a central role in the non-canonical mTORC1 complex, which acts independently of RHEB and specifically mediates phosphorylation of MiT/TFE factors TFEB and TFE3: GDP-bound RagD/RRAGD mediates recruitment of MiT/TFE factors TFEB and TFE3.
Synonyms: RagD; DKFZP761H171; bA11D8.2.1; HOMG7
Tractability: Small molecule: a structure with a bound ligand is known. PROTAC: ubiquitination databases record sites on it; its protein half-life has been measured.
Gene: Protein-coding gene on chromosome 6 (89,364,616 to 89,412,735, reverse strand). Ensembl gene ENSG00000025039.
Subcellular location: Cytoplasm; Nucleus; Lysosome membrane
Subcellular location (Human Protein Atlas): Nucleoplasm; Centrosome; Vesicles
Pathways (Reactome):
Signal Transduction: Energy dependent regulation of mTOR by LKB1-AMPK; MTOR signalling; Regulation of PTEN gene transcription; mTORC1-mediated signalling
Autophagy: Macroautophagy
Cellular responses to stimuli: Amino acids regulate mTORC1
Gene Ontology:
Molecular function: GDP binding; GTP binding; GTPase activity; GTPase binding; molecular adaptor activity; protein binding; protein heterodimerization activity
Biological process: cellular response to L-leucine; cellular response to leucine starvation; positive regulation of TORC1 signaling; cellular response to amino acid stimulus; cellular response to starvation; intracellular protein localization; negative regulation of autophagy; positive regulation of TOR signaling; cellular response to amino acid starvation; response to amino acid
Cellular component: cytoplasm; Gtr1-Gtr2 GTPase complex; lysosomal membrane; lysosome; nucleoplasm; nucleus; cytosol
Genetic constraint (gnomAD): Loss-of-function variants: 11 observed, 28.91 expected, observed/expected ratio (o/e) 0.38, 90% interval 0.24 to 0.63. The upper end of that interval is the gene's LOEUF score, 0.63, which puts it in group 2 of 6, group 1 being the genes least tolerant of losing a copy. Missense variants: 305 observed, 443.1 expected, observed/expected ratio (o/e) 0.69, 90% interval 0.63 to 0.76. Synonymous variants: 141 observed, 160.02 expected, observed/expected ratio (o/e) 0.88, 90% interval 0.77 to 1.01.
Homologues: Orthologues: chimpanzee RRAGD (100% identical), macaque RRAGD (99% identical), dog RRAGD (97% identical), pig RRAGD (97% identical), mouse Rragd (95% identical), rat Rragd (94% identical), rabbit RRAGD (89% identical), tropical clawed frog rragd (86% identical), guinea pig RRAGD (85% identical), zebrafish rragd (78% identical), zebrafish rragca (77% identical), zebrafish rragcb (75% identical), and 2 more. Paralogues in human: RRAGC (77% identical), RRAGB (22% identical), RRAGA (20% identical).
Diseases named in the same sentence as RRAGD in open-access papers:
RRAGD is named in the same sentence as 24 diseases in open-access papers, as found by Europe PMC text mining. Sharing a sentence is not in itself a finding about the gene and the disease. The quoted sentences say what the papers report.
cardiomyopathy (4 papers, 2023 to 2025). A disease of the heart muscle or myocardium proper. "Mutations in the RRAGD gene are causative of an autosomal dominant disorder characterized by kidney tubulopathy and cardiomyopathy." (PMID 37188688, 2023). "Importantly, constitutive phosphorylation of MiT/TFE factors induced by RRAGD mutations leads to their cytoplasmic retention, strongly suggesting that MiT/TFE inhibition is the main mechanism underlying kidney tubulopathy and cardiomyopathy." (PMID 37188688, 2023). "Similarly, another study found that a missense mutation in RRAGD impairs RAGD GTP-binding leading to a constitutively activated mTORC1 even in amino acid-depleted conditions in patients with Kidney Tubulopathy and Cardiomyopathy." (PMID 36929165, 2023).
melanoma (4 papers, 2017 to 2025). A malignant, usually aggressive tumor composed of atypical, neoplastic melanocytes. "LINC00622 physically associates with BTF3 and binds to the RRAGD locus to transcriptionally enhance RRAGD expressions and further activate mTORC1 to inhibit autophagic cell death, which contributes to melanoma progression." (PMID 40651979, 2025). "Our findings not only demonstrated the oncogenic role of LINC00622 via RRAGD/mTORC1 axis to repress autophagic cell death in cutaneous melanoma, but also offer novel treatment targets for melanoma therapy." (PMID 40651979, 2025). "Specifically, RRAGD has been reported to be one of several genes differentially expressed in human melanoma cell lines and considered as a promising target for diagnostic and therapeutic investigations." (PMID 40651979, 2025). "Collectively, the in vivo experiments indicated that LINC00622 suppresses autophagy by repressing RRAGD expression and further inhibiting mTORC1-mediated autophagic cell death to promote melanoma progression." (PMID 40651979, 2025). "Mechanistic study indicated that LINC00622 transcriptionally enhances RRAGD to repress mTORC1-modulated autophagic cell death to promote melanoma development." (PMID 40651979, 2025). "The expression of RRAGD together with partner RRAGC were checked in melanoma tumors and cells." (PMID 40651979, 2025). "Depletion of RRAGD significantly increased the amount of LC3B-II and reduced P62 expression in melanoma cells, which indicates the enhancement of autophagic flux." (PMID 40651979, 2025). "The correlation between MITF and RRAGD and FNIP2 mRNA expression was reproduced using The Cancer Genome Atlas (TCGA) melanoma cohort." (PMID 41275493, 2025).
dilated cardiomyopathy (3 papers, 2024 to 2025). Cardiomyopathy which is characterized by dilation and contractile dysfunction of the left and right ventricles. "mTOR inhibition has been proposed as a potential treatment strategy to prevent dilated cardiomyopathy due to pathogenic RRAGD variants." (PMID 41141537, 2025). "Variants in the Ras-related GTPase D (RRAGD) gene have been associated with autosomal dominant kidney hypomagnesemia (ADKH) characterized by hypokalemia, nephrocalcinosis, and dilated cardiomyopathy (DCM)." (PMID 41141537, 2025). "However, a reanalysis of the ES data in January 2022 identified a VUS in RRAGD (Ras-related GTP binding D, HGNC:19903), a gene newly associated in November 2021 with hypomagnesemia, tubulopathy, and dilated cardiomyopathy." (PMID 38790019, 2024).
liver cancer (3 papers, 2017 to 2021). An epithelial or non-epithelial malignant neoplasm that arises from the liver. "RRAGD misregulation is correlated with renal and liver cancer prognosis." (PMID 30333515, 2018).
hepatocellular carcinoma (2 papers, 2023 to 2024). A malignant tumor that arises from hepatocytes. "Elevated RRAGD expression has been reported in human hepatocellular carcinoma." (PMID 38339062, 2024).
Hypokalemia (2 papers, 2023 to 2025). An abnormally decreased potassium concentration in the blood. "Recently, we identified gain-of-function variants in the RRAGD gene as the cause of ADKH, which is associated with hypokalemia, salt wasting, hypercalciuria, and nephrocalcinosis." (PMID 41141537, 2025).
cutaneous melanoma (1 paper, 2025). A primary melanoma arising from atypical melanocytes in the skin. "Our findings demonstrate that upregulated LINC00622 acts as a key regulator to transcriptionally enhance RRAGD expression and represses mTORC1-regulated autophagy by associating with BTF3 in cutaneous melanoma." (PMID 40651979, 2025). "Mechanistically, LINC00622 associates with and recruits BTF3 to transcriptionally enhance RRAGD expression for activating mTORC1 and thus inhibiting autophagic cell death, which contributes to the development of cutaneous melanoma." (PMID 40651979, 2025).
lymphoma (1 paper, 2025). A malignant (clonal) proliferation of B- lymphocytes or T- lymphocytes which involves the lymph nodes, bone marrow and/or extranodal sites. "We show that IL4 treatment induced RRAGD expression, that RRAGD is required for mTOR activation in lymphoma cells and that IL4-enhanced BCR signaling induced mTOR activation." (PMID 39910284, 2025).
prostate carcinoma (1 paper, 2020). A carcinoma that arises from epithelial cells of the prostate gland. "In prostate cancer, genetic alterations in RRAGA and RRAGC genes that encode RAGA and RAGC respectively are uncommon, however RRAGB (encoding RAGB) is amplified in up to 7.7% of cases and RRAGD (encoding RAGD) deep deletion occurs in 6.5–14.4% of cases." (PMID 32630372, 2020). "Common genetic alterations within the three prostate cancer datasets analyzed were observed in PTEN, DEPTOR, SGK3, FOXO1/3, MAP3K7, RRAGD, SESN1, PIK3CA, PIK3C2B, and PDPK1." (PMID 32630372, 2020).
Sepsis (1 paper, 2023). Sepsis is defined as life-threatening organ dysfunction caused by a dysregulated host response to infection. "Among them, the AUCs of ITGAM, KIF1B, RRAGD, S100A9, SCOC, and SPTLC2 in the internal and external test sets were more than 0.6, indicating diagnostic significance for sepsis." (PMID 37834169, 2023).
tumor (14 papers, 2017 to 2024). "Our results showed that RRAGD expression was distinct between tumor and control tissues, and elevated in the high-risk score groups, which indicates and contributes to the poor prognosis of HCC patients." (PMID 38468074, 2024). "From animal experiments, when LncTUG1 was knocked down, miR-144-3p increases while the expression of RRAGD, mTOR and S6K reduced in neoplasm tissues, and the neoplasm volume is also reduced." (PMID 37160972, 2023). "In addition, IHC staining certificated that the RRAGD expression decreased in neoplasms from mice injected with sh-TUG1-expressing Huh7 cells." (PMID 37160972, 2023). "RRAGD promoted mTORC1 activity and tumor growth, influencing the T-cell similarly." (PMID 32419983, 2020). "This yielded 88 genes associated with tumor grade, in which seven DEGs (C8orf33, TSNAXIP1, TM4SF1, CTH, ANXA2, KIAA1522 and LRRC1) can distinguish HCC of G3 from G1, two DEGs (CYB5A and RRAGD) can distinguish HCC of G3 from G2, and two DEGs (CFHR4 and F13B) can distinguish HCC of G3 from G4." (PMID 29123978, 2017). "Next we examined whether the neoplasm inhibitory effect of miR-144-3p involves RRAGD." (PMID 37160972, 2023). "Studies showed that the Rag GTPases (RRAGD) could regulate the mTORC1 signaling pathway by regulating the translocation of mTORC1 to the site of activation (lysosomal surface) and result in suppression of the folliculin tumor." (PMID 36500178, 2022). "Results showed that the mRNA levels of BNIP3, CYCS, RRAGD, CD44, EIF4E, MAP4K1, and LIN28B were higher in tumor samples, whereas the mRNA levels of PPARGC1A and FLT3 were higher in normal samples." (PMID 38468074, 2024). "It’s found that IHC signals of BNIP3, CYCS, RRAGD, CD44, EIF4E, and MAP4K1 were consistently high in tumor cells of HCC, compared with normal tissues, implying that these genes were indeed ectopically expressed in HCC." (PMID 38468074, 2024).
cancer (5 papers, 2020 to 2025). A tumor composed of atypical neoplastic, often pleomorphic cells that invade other tissues. "RRAGD can promote cell proliferation, invasion, migration, aerobic glycolysis, and Warburg effect (an important characteristic of cancer cell metabolism) of HCC." (PMID 35646665, 2022). "In the Cancer Cell Line Encyclopedia (CCLE), expression of FNIP2 and RRAGD, and to some extent RRAGC, but not RRAGA or RRAGB, correlates with MITF expression." (PMID 41275493, 2025).
kidney diseases (1 paper, 2024). "Biological annotation found evidence for three novel decline-associated loci to capture common-variant-effects for genes of rare Mendelian kidney diseases (SDCCAG8, RRAGD, and MUC1), additional to the two such genes in known eGFR-decline loci (UMOD, PRKAG2)." (PMID 39567532, 2024).
RRAGD also shares sentences with these, for which no sentence is quoted: Hypomagnesemia (2 papers); Ataxia (1); atherosclerosis (1); benign skin tumors (1); breast carcinoma (1); colon cancer (1); colon tumor (1); follicular lymphoma (1); Hypercalciuria (1); nephrocalcinosis (1); prostate adenocarcinoma (1).